ENSG00000286804 (novel transcript, sense intronic to FBXO16)
Gene: Long non-coding RNA gene on chromosome 8 (28,414,499 to 28,416,593, reverse strand). Ensembl gene ENSG00000286804.
Gene Ontology:
Molecular function: U4 snRNA binding
Biological process: formation of quadruple SL/U4/U5/U6 snRNP; spliceosomal tri-snRNP complex assembly
Cellular component: U4/U6 x U5 tri-snRNP complex; U6 snRNP